ALB (albumin)
Diseases named in the same sentence as ALB in open-access papers (continued):
Sharing a sentence is not in itself a finding about the gene and the disease.
hyperuricemia (continued). "Hyperuricemia could induce renal arteriopathy and reduce renal blood flow, while increasing urinary albumin excretion, which is correlated with plasma xanthine oxidoreductase (XOR) activity." (PMID 37238929, 2023). "In addition, age, segmental glomerulosclerosis, tubular atrophy/interstitial fibrosis, proteinuria, eGFR, hyperuricemia, albumin, and treatment were also significantly related to the development of composite end point." (PMID 34869465, 2021). "In hyperuricemia men, serum UA was an explanatory variable for serum glycated albumin." (PMID 33426022, 2020). "Additionally, we detected raised albumin and SH group levels, denoting the significance of hyperuricemia induced oxidative stress in the pathogenesis of NASH." (PMID 31163711, 2019). "Increases in total serum protein concentrations were positively associated with hyperuricaemia, while increases in serum albumin concentrations exhibited a negative association." (PMID 29852506, 2018). "A decreased serum albumin level (<3.5 g/dL) was the most significant factor associated with significant fibrosis (OR = 40.0, 95% CI = 4.5–300, P = 0.001), followed by the absence of hyperuricemia (OR = 5.6, 95% CI = 1.5–21.7, P = 0.01)." (PMID 26441244, 2015). "Previous randomised controlled trials have demonstrated that both febuxostat and topiroxostat decreased urinary albumin levels in patients with stage 3 CKD and hyperuricaemia." (PMID 39881083, 2025). "The mediation analysis in this study revealed that the Planetary Health Diet Index (PHDI-Dairy) influences hyperuricemia (HUA) partly through the improvement of kidney function, as indicated by the urinary albumin-to-creatinine ratio (UACR)." (PMID 41031353, 2025). "Among them, ESR1 has the most frequent gene connections (D = 36), followed by ALB (D = 24) and APOA1 (D = 11), indicating their key roles in both hyperuricemia and HFrEF." (PMID 35911515, 2022). "Low serum albumin level, high BUN/Cr ratio, and hyperuricemia were also independent predictors for early initiation of dialysis." (PMID 34219598, 2021). "The recruited factors included age, sex, BMI, MetS components, albumin level, rGT level, ALT level, HOMA-IR, and the presence of hyperuricemia (defined as ≥ 7 mg/dL for men and ≥ 6.0 mg/dL for women)." (PMID 26441244, 2015). "A significant negative association was also observed between hyperuricemia and MCI in individuals with albumin levels ≥40 g/L (OR = 0.48, 95% CI = 0.22–0.96, p = 0.049)." (PMID 40166637, 2025). "Urinary albumin-creatinine ratio (ACR) in patients with hyperuricemia was compared with those without hyperuricemia." (PMID 37612612, 2023). "However, after further adjustment for hyperuricemia, TC, HDL-C, albumin, creatinine, BUN, and HbA1c, this association was no longer significant." (PMID 37996718, 2024).
Protein-losing enteropathy (58 papers, 2006 to 2026). Abnormal loss of protein from the digestive tract related to excessive leakage of plasma proteins into the lumen of the gastrointestinal tract. "Hepatic congestion due to elevated venous pressures impairs liver function and albumin synthesis, while severe venous congestion can lead to protein-losing enteropathy, compounding albumin loss." (PMID 40703630, 2025). "The accumulation of fluid in these compartments, aggravated by the low serum albumin due to loss of fluid and protein losing enteropathy, result in clinical deterioration over a matter of months." (PMID 36238151, 2022). "In patients with protein-losing enteropathy, protein loss via the gastrointestinal mucosa will increase to almost 60% of the total albumin." (PMID 34797336, 2021). "Protein losing enteropathy (PLE) is characterised by enteric loss of proteins including albumin, immunoglobulins and clotting factors." (PMID 29623675, 2018). "This case shows strong circumstantial evidence that the eosinophilic enterocolitis and protein-losing enteropathy were caused by the Mn leak from a retained disk battery; she was completely asymptomatic before battery ingestion with normal albumin levels and eosinophil counts before battery removal." (PMID 18752666, 2008). "The initially normal albumin and total protein levels at ED admission decreased suddenly, presumed to be due to the toxicity of protoanemonin and saponin of C. palustris causing mucosal injury and consequently serum protein loss via the gastrointestinal tract, that is, protein-losing enteropathy." (PMID 34797336, 2021). "Sequential abdominal scintigraphy using 99mTc-albumin demonstrated progressive protein-losing enteropathy, supporting the diagnosis." (PMID 41494000, 2026). "Plasma albumin concentration is a key prognostic biomarker in protein-losing enteropathies, with one study reporting that normalization within 50 days of treatment initiation was associated with a longer survival time." (PMID 40872702, 2025). "This aligns with marked endoscopic lesions in the duodenum and severe CIE, with secondary protein-losing enteropathy (serum albumin concentrations < 20 g/L) being predictive of more severe disease and negative outcomes." (PMID 39238011, 2024). "One of these dogs was also suffering from protein-losing enteropathy (PLE) with a serum albumin concentration below 20 g/L." (PMID 37104426, 2023). "In protein losing enteropathy patients serial albumin replacements sometimes are required to increase oncotic pressure and alleviate edemas and effusions." (PMID 36911024, 2023). "Total protein and albumin were normal in all but one patient with refractory protein losing enteropathy." (PMID 35346249, 2022). "Laboratory tests should include serum total protein and albumin, hemoglobin/hematocrit, iron, IgE specific for milk and/or other offending foods, and fecal α1AT for protein-losing enteropathy." (PMID 35174199, 2022). "At the age of 28 he developed bilateral pleural effusions and evidence of a protein losing enteropathy i.e., intestinal lymphangiectasia, with low albumin, low immunoglobulins and raised faecal alpha 1-antitrypsin levels." (PMID 36238151, 2022). "Usually, both albumin and globulin are lost from the intestines in protein-losing enteropathies, especially where there is a marked villous atrophy." (PMID 34679072, 2021). "Three patients had protein-losing enteropathy where 2 had markedly reduced albumin levels (both 23 g/L),and one patient had slightly reduced albumin 36 g/l." (PMID 33688987, 2021). "In dogs with protein-losing enteropathy, a severe enteropathy leading to hypoproteinemia, tryptophan was the only serum amino acid found to be decreased, and correlated with serum albumin concentrations." (PMID 34573464, 2021). "Congenital protein losing enteropathy results in a low ALB level due to protein-losing enteropathy and severe diarrhea." (PMID 31057599, 2019).
Protein-losing enteropathy (continued). "Serum albumin is a marker of both protein-losing enteropathy and liver function, and has been proposed, along with ESR, as a primary determinant of vitamin D status in inflammatory bowel disease." (PMID 28192499, 2017). "Protein losing enteropathy was suspected due to the combination of low albumin and reduced serum levels of IgA, IgG, IgM, and transferrin combined with gastrointestinal symptoms." (PMID 27891267, 2016). "ΔIEC mice also showed lymphocytopenia and increased levels of faecal albumin, consistent with a protein-losing enteropathy." (PMID 27187615, 2016). "While albumin decline likely reflects protein-losing enteropathy and enhanced catabolism, DUOX2 upregulation may exacerbate mucosal damage and inflammation, reinforcing a vicious cycle." (PMID 41383848, 2025). "In protein-losing enteropathy, serial albumin replacements may become necessary in some patients to increase oncotic pressure and alleviate edemas." (PMID 39131972, 2024). "Additional laboratory examinations with liver enzymes, platelet counts, liver synthesis parameters (protein, albumin, cholinesterase, coagulation) as well as stool examinations for protein-losing enteropathy (PLE, alpha-1-antiotrypsin) should be performed accordingly." (PMID 37711600, 2023). "However, in dog 3, who had the lowest albumin at the start of the study, there was suspicion of a pre-existing protein-losing enteropathy (PLE)." (PMID 32784359, 2020). "Humans with IBD may have low serum protein levels (e.g. albumin) which is often assumed to be due to damage to mucosa that results in a protein-losing enteropathy." (PMID 27045690, 2016). "Protein-losing enteropathy is a cause of secondary hypogammaglobulinemia and is associated with a low albumin as well as nonspecific serum protein loss." (PMID 17194183, 2006). "Thus, albumin was chosen for volume replacement in this case in order to maintain intravascular volume and to prevent third spacing of fluid given the diminished oncotic pressure from protein losing enteropathy." (PMID 23227367, 2012). "Since we assessed serum albumin levels on admission, low albumin is not a consequence of protein-losing enteropathy (i.e. low albumin is not secondary to CDI) and should be considered a possible predisposing factor for CDI development." (PMID 25899507, 2015). "At 6 months follow-up, the patient has remained well, with normal albumin levels and no symptoms of protein-losing enteropathy." (PMID 18752666, 2008). "This interesting datum agrees with a previous study in a different species, using vein inoculation of radioactively labeled albumin, showing that the albumin found in the feces does not derive from plasma unless the enteropathy is specifically a (chronic) protein-losing enteropathy." (PMID 36977272, 2023). "However, in the present study, albumin concentration was higher in the AD group, although vitamin B12 was decreased; hence, it is not possible to attribute these changes to protein-losing enteropathy." (PMID 32674496, 2020). "In addition, there were no changes in serum total protein or albumin concentrations which could indicate protein-losing enteropathy." (PMID 29179750, 2017).
peripheral arterial disease (57 papers, 2011 to 2026). A disorder of the arteries supplying the upper and lower extremity and the visceral organs. "In addition, previous studies have found that low albumin levels are an independent risk factor for amputation in patients with peripheral arterial disease." (PMID 37559005, 2023). "Given the shared albumin component, two separate multivariable logistic regression models were constructed to evaluate independent associations, adjusting for age, peripheral arterial disease (PAD), and index amputation level." (PMID 42123010, 2026). "In the present study, the mean values of both serum protein and albumin were lower in the subjects with peripheral arterial disease." (PMID 35951636, 2022). "Abnormal atherosclerotic conditions, i.e. arterial stiffness, carotid plaques and peripheral artery disease, was more common at a U-albumin/creatinine ratio (U-ACR) > 15 mg/g (~ equivalent to 1,5 mg albumin/mmol creatinine)." (PMID 32758145, 2020). "In the multivariate analyses, risk factors associated with foot ulceration included previous amputation (OR, 10.19 [CI, 3.14 to 33.07]), peripheral arterial disease (OR, 6.16 [CI, 1.47 to 25.80]), and serum albumin (OR, 0.87 [CI, 0.78 to 0.96])." (PMID 28886703, 2017). "For ulceration, the odds increased if participants had a history of amputation or peripheral arterial disease, and fell as serum albumin increased." (PMID 28886703, 2017). "Dialysis patients with markedly higher risks of foot ulceration and/or amputation include those with previous or current ulceration, past amputation, peripheral arterial disease, lower serum albumin, and foot deformity." (PMID 28886703, 2017). "There are markedly higher risks of foot ulceration and/or amputation in those with previous and/or current ulceration, previous amputation, peripheral arterial disease, lower serum albumin, and foot deformity." (PMID 28886703, 2017). "Factors associated with foot ulceration were previous amputation (OR, 10.19), peripheral arterial disease (OR, 6.16) and serum albumin (OR, 0.87); whereas previous and/or current ulceration (OR, 167.24 and 7.49, respectively) and foot deformity (OR, 15.28) were associated with amputation." (PMID 28886703, 2017). "This review identified peripheral arterial disease, neuropathy, high Wagner’s grade, osteomyelitis, postprandial glucose level, white cell count, c-reactive protein, erythrocyte sedimentation rate, low hemoglobin, and albumin as the most significant predictors of amputation." (PMID 36035032, 2022).
Crohn disease (56 papers, 2010 to 2026). A gastrointestinal disorder characterized by chronic inflammation involving all layers of the intestinal wall, noncaseating granulomas affecting the intestinal wall and regional lymph nodes, and transmural fibrosis. "For Crohn’s disease (CD), low level of preoperative nutritional indicators such as body mass index (BMI), hemoglobin and albumin are independent risk factors of postoperative complications." (PMID 29335491, 2018). "Female gender, low BMI, low albumin level, the presence of comorbidities, diverticulosis, Crohn’s disease, and admission to an ICU are also acknowledged to be risk factors in several studies." (PMID 29416554, 2018). "Recent guidelines advocate BMI <18.5 kg/m2, weight loss >10–15% within six months and serum albumin <30 g/L as best reflectors of severe undernutrition in Crohn’s disease." (PMID 28587182, 2017). "Additionally, low serum albumin has been found to be a risk factor for low bone mineral density, a recognized complication of Crohn’s disease in humans." (PMID 24324827, 2013). "Conversely, patients in the Crohn’s disease group demonstrated significantly worse nutritional status, as mean albumin levels were 3.7 ± 0.5 in the right-sided colon carcinoma group compared with 3.4 ± 0.5 in the Crohn’s disease patients (p = 0.005)." (PMID 38792351, 2024). "In this study, we used C‐reactive protein (CRP) and fecal (f‐) calprotectin (established markers) and serum albumin (explorative marker) as distinct markers of inflammatory activity in Crohn's disease patients on maintenance treatment." (PMID 32514446, 2020). "Δ albumin is a better prognostic marker for an eventful postoperative course after laparoscopic surgery in patients with Crohn’s disease in comparison to albumin alone." (PMID 30422980, 2018). "Little is known about the perioperative dynamic of albumin and its effect on surgical outcome in Crohn’s disease." (PMID 30422980, 2018). "Our data has identified that lower preoperative pre-albumin, longer duration of operation and higher intraoperative lactate level are risk factors for SSI in patients with Crohn’s disease receiving definitive bowel resection." (PMID 28852175, 2017). "Yet, these patients suffered from malignancies or severe Crohn’s disease, which impeded full recovery of their health status, including increase of albumin level." (PMID 22669399, 2012). "However, this picture is complicated by the nutritional status of the Crohn’s disease cohort, as they had a lower BMI as well as lower albumin concentrations compared to patients with right-sided colon carcinoma." (PMID 38792351, 2024). "Low vitamin D was associated with partial Mayo scores and C‐reactive protein (CRP) to albumin ratio in ulcerative colitis, and CRP and CRP/albumin ratio in Crohn's disease." (PMID 38162852, 2023). "Researchers have also identified several factors that may be associated with subsequent surgery, including longer disease duration, higher Crohn’s disease activity indexes, higher levels of C-reactive protein, lower levels of albumin, abscess, and bowel stricture." (PMID 40674301, 2025). "In conclusion, Mann-Whitney U test showed that absolute monocyte count, PLT, absolute neutrophil count, ESR, CRP, PT, D-Dimer, TBIL, ALB, HCT, Hb were correlated with disease activity of Crohn’s disease." (PMID 38598519, 2024). "For instance, patients with higher albumin tend to have higher triceps skinfold measurements reflecting upper arm muscle circumference and lower hs-CRP levels in those with Crohn’s disease." (PMID 37964931, 2023). "We investigated the rate of continuous treatment of mesalazine granules and examined the changes in Crohn’s Disease Activity Index (CDAI) and serum C-reactive protein (CRP), albumin, and hemoglobin (Hb) levels 2 years after the switch." (PMID 33288852, 2020).
Crohn disease (continued). "The variables used were Crohn’s Disease Activity Index (CDAI) for patients with Crohn’s Disease (CD) and fecal calprotectin (FC), C-Reactive Protein (CRP), and albumin (ALB) for patients with IBD." (PMID 33375314, 2020). "The variables used were Crohn’s Disease Activity Index (CDAI), albumin, body weight (BW), and postoperative complications (COM)." (PMID 31766687, 2019). "The related clinical information included Crohn disease (CD), ulcerative colitis (UC), extent, behavior, complication, active index, Hs-CRP, ESR, platelet count, BMI, hemoglobin value, albumin levels, and CDEIS." (PMID 28538364, 2017). "We investigated the height, body weight, serum levels of albumin, IGF-I, CRP, and cytokines, and the amount of corticosteroid administered in children with Crohn's disease (CD, n = 15) and ulcerative colitis (UC, n = 18)." (PMID 20454571, 2010). "Some clinical and serological parameters, including Crohn’s Disease Activity Index (CDAI), CRP levels, ESR, ALB levels, neutrophil to lymphocyte ratio (NLR), platelet to lymphocyte ratio (PLR), and CRP to ALB ratio (CAR), are reported associated with MH in patients with CD." (PMID 40630487, 2025). "•MDA, PON-1, CAT, albumin, transferrin, and TAC indicate Crohn's disease flares." (PMID 39368456, 2024). "Binomial logistic regression analysis identified seven clinical variables with a p-value less than 0.01, including Biomarker (B), Waist-to-Height Ratio (WHtR), Intestinal obstruction, Albumin (ALB), Crohn's Disease Activity Index (CDAI), Myocardial Flow Index (MFI), and C-reactive protein (CRP)." (PMID 38480778, 2024). "C-reactive protein to albumin ratio (CAR), a composite indicator of inflammation and nutritional status, has recently been recognized as an independent prognostic marker in malignancy, Crohn’s disease, critically ill patients and vasculitides." (PMID 37223604, 2023). "A total of 876 IBD patients, composed of 275 patients with ulcerative colitis (UC) and 601 patients with Crohn's disease (CD), were included in this retrospective study, and the serum C-reactive protein (CRP), albumin (ALB), erythrocyte sedimentation rate (ESR), and CBC parameters were measured." (PMID 32655630, 2020). "Serum albumin levels have not been widely used as a marker of disease activity in Crohn's disease." (PMID 32514446, 2020).